IGF2BP2 (insulin like growth factor 2 mRNA binding protein 2)
Diseases named in the same sentence as IGF2BP2 in open-access papers (continued):
Sharing a sentence is not in itself a finding about the gene and the disease.
hypopharyngeal tumors (1 paper, 2021). "The results from the in vivo studies were consistent with those of the in vitro experiments, demonstrating that both inhibition of PD-L1 and knockdown of IGF2BP2 could significantly reduce the growth of hypopharyngeal tumors." (PMID 34608837, 2021). "Thus, it was hypothesized that IGF2BP2 may bind to PD-L1 mRNA, affecting PD-L1 and PD-1 protein expression, thereby serving a role in the progression of hypopharyngeal neoplasms." (PMID 34608837, 2021). "Therefore, as with PD-L1 inhibition, IGF2BP2 knockdown may inhibit PD-1 expression via binding to PD-L1 mRNA, ultimately reducing the progression of hypopharyngeal neoplasms." (PMID 34608837, 2021).
ischemia (1 paper, 2023). A hypoperfusion of the BLOOD through an organ or tissue caused by a PATHOLOGIC CONSTRICTION or obstruction of its BLOOD VESSELS, or an absence of BLOOD CIRCULATION. "When we analyzed the data that had been previously obtained from these mice, we found that IGF2BP2 RNA expression was upregulated over 4-fold as a result of this induced ischemia." (PMID 38052926, 2023).
laryngeal carcinoma (1 paper, 2019). Carcinoma that arises from the laryngeal epithelium. "A comparison of the prognosticators identified for tongue and laryngopharynx indicated that AP2M1 and IGF2BP2 are common across sites, with deregulation of AP2M1, a protein trafficking molecule, signifying contradictory effects in tongue and laryngeal cancer." (PMID 31310629, 2019).
Lewis lung carcinoma (1 paper, 2026). "In vivo, deletion of IGF2BP2 specifically in the myeloid lineage was sufficient to reduce tumor growth in a subcutaneous Lewis lung carcinoma model, accompanied by decreased TAM infiltration and a shift towards a pro-inflammatory macrophage phenotype." (PMID 41943844, 2026).
lymphatic system cancer (1 paper, 2022). "We observed that IGF2BP2 and IGF2BP3 expression was markedly upregulated in the central nervous system (CNS), lung, gastric tract, head, neck, pancreas, and lymphatic system cancers." (PMID 36686749, 2022).
male infertility (1 paper, 2025). The inability of the male to effect fertilization of an ovum after a specified period of unprotected intercourse. "For instance, one study explored the role of IGF2BP2 in male infertility by examining its regulation of PLOD2 mRNA stability." (PMID 40949795, 2025).
meningioma (1 paper, 2023). A generally slow growing tumor attached to the dura mater. "In vitro experiments verified that the mRNA and protein expression levels of METTL3 and IGF2BP2 were lower in meningioma cells than in normal meningioma cells." (PMID 37910780, 2023). "Low expression of METTL3 and IGF2BP2 in meningioma cells (vs. normal meningioma cells) was also confirmed at the transcriptional and translational levels." (PMID 37910780, 2023). "In conclusion, two m6A methylated genes (METTL3 and IGF2BP2) were identified and a RiskScore methylation regulatory network was constructed, which can be considered prognostic factors for meningioma." (PMID 37910780, 2023). "In addition, low expression of METTL3 and IGF2BP2 in meningioma cells was verified by western blotting." (PMID 37910780, 2023). "In this study, METTL3 and IGF2BP2 were identified as crucial m6A genes for meningioma prognosis." (PMID 37910780, 2023). "Therefore, central regulators of m6A methylation (METTL3 and IGF2BP2) could potentially serve as novel therapeutic targets in meningioma." (PMID 37910780, 2023).
myocardial infarction (1 paper, 2023). Gross necrosis of the myocardium, as a result of interruption of the blood supply to the area, as in coronary thrombosis. "IGF2BP2 is also upregulated in DCM or myocardial infarction patients." (PMID 38052926, 2023).
nephritis (1 paper, 2024). Inflammation of renal tissue. "For example, METTL3 increased the m6A modification of TAB3 and promoted the stability of TAB3 in an IGF2BP2-dependent mechanism, leading to the development of nephritis." (PMID 39337381, 2024).
nonalcoholic fatty liver disease (1 paper, 2018). "Moreover, IGF2BP2 may also be involved in pathological conditions preceding HCC, such as nonalcoholic fatty liver disease (NAFLD)." (PMID 29736175, 2018).
Parkinson disease (1 paper, 2025). A progressive degenerative disorder of the central nervous system characterized by loss of dopamine producing neurons in the substantia nigra and the presence of Lewy bodies in the substantia nigra and locus coeruleus. "In Parkinson’s disease mouse models, both gene expression and protein levels of ALKBH5 and IGF2BP2 in the substantia nigra were upregulated, which in consistent with the trend of ALKBH5 upregulation observed in aging cochleae, suggesting that ALKBH5 may play a significant role in geriatric disease." (PMID 40198960, 2025).
prostate tumors (1 paper, 2021). "Seven regulators, including IGF2BP2, METTL3, METTL16, ZNF217, ZC3H13, RBM15B, and PRRC2A, exhibited significant correlations between CNVs and gene expression levels in prostate tumors." (PMID 34899855, 2021).
rectal cancer (1 paper, 2022). A primary or metastatic malignant neoplasm that affects the rectum. "Interestingly, SFN and IGF2BP2, which were more highly expressed in the metastases of poor-outcome patient I, were also associated with shorter overall survival in a large cohort (n = 165) of rectal cancer patients based on data from the Kaplan–Meier plotter database." (PMID 35565214, 2022).
Salmonella Infections (1 paper, 2020). Infections with bacteria of the genus SALMONELLA. "Finally, the GO and KEGG analyses of biologically enriched genes that were positively correlated with IGF2BP2 and IGF2BP3 expression revealed the top 10 relevant biological processes, including cell junction organization, salmonella infection, mitotic nuclear division, and cell cycle." (PMID 33246429, 2020).
sarcopenia (1 paper, 2021). Progressive decline in muscle mass due to aging which results in decreased functional capacity of muscles. "In conclusion, this study revealed that the overexpression of Igf2bp2 in C2C12 cells using a let-7e-5p inhibitor improves sarcopenia mainly via suppression of genes associated with muscle atrophy and enhanced mitochondrial function." (PMID 35002969, 2021).
steatosis (1 paper, 2020). Increased lipid within the cytoplasm of cells. "Further, transgenic overexpression of the IGF2 mRNA binding protein (IGF2BP2/IMP2), leading to upregulated expression of H19, induces steatosis and promotes NASH progression." (PMID 32429417, 2020).
Thyroid adenoma (1 paper, 2014). The presence of a adenoma of the thyroid gland. "In total, 12 of the 65 reported T2D GWAS loci are significantly differentially methylated (FDR 25%), and these include well-documented T2D loci such as those near IGF2BP2 (Insulin-like growth factor 2 mRNA-binding protein 2) and THADA (thyroid adenoma-associated gene)." (PMID 25502755, 2014).
tongue SCC (1 paper, 2025). "The oncogenic functions of IGF2BP2 were evaluated through tissue microarrays, CCK-8, transwell assays, mouse xenografts, and Igf2bp2-deficient mouse models of tongue SCC (TSCC)." (PMID 40362183, 2025).
viral infections (1 paper, 2022). "There is no current evidence of a direct role of IGF2BP2 in the response against viral infections, but recent data connected its function to the lncRNAs." (PMID 35664076, 2022).
ZIKV infection (1 paper, 2024). "To study the impact of ZIKV infection on IGF2BP2 association with endogenous RNAs, we decided to focus our analysis on three known IGF2BP2 mRNA ligands namely CIRBP, TNRC6A, and PUM2." (PMID 39565347, 2024). "Our interactome analysis revealed global changes in the composition of IGF2BP2 RNP with 62 cellular proteins whose association with IGF2BP2 was altered during ZIKV infection." (PMID 39565347, 2024). "We have also demonstrated that ZIKV infection specifically induces the association between IGF2BP2 and ATL2, an ER-shaping protein which was previously reported to be required for DENV and ZIKV replication." (PMID 39565347, 2024). "The fact that ZIKV infection promotes IGF2BP2 association with ATL2 led us to hypothesize that IGF2BP2 regulates vRNA replication by contributing to ZIKV replication organelle biogenesis." (PMID 39565347, 2024). "Altogether, these data show that ZIKV infection specifically alter the composition of IGF2BP2 RNP complex." (PMID 39565347, 2024). "In line with our gene ontology analysis, one of these clusters comprised proteins involved in mRNA splicing for most of which interaction with IGF2BP2 was significantly decreased during ZIKV infection (red circles)." (PMID 39565347, 2024). "Gene ontology analysis of the 62 partners whose interaction with IGF2BP2 was altered during ZIKV infection revealed a high enrichment of biological processes related to mRNA splicing." (PMID 39565347, 2024). "(C) Interaction tree of the 62 IGF2BP2 interactions modulated by ZIKV infection (generated with STRING online resource)." (PMID 39565347, 2024). "(B) Gene ontology (GO) biological process analyses of the IGF2BP2 interactions which were impacted upon ZIKV infection." (PMID 39565347, 2024). "Most notably, ZIKV infection decreased IGF2BP2 interaction with 15 proteins of the mRNA splicing machinery." (PMID 39565347, 2024). "Following the observations that IGF2BP2 is a ZIKV host dependency factor, we investigated the impact of ZIKV infection on IGF2BP2 expression and subcellular distribution." (PMID 39565347, 2024). "Comparable amounts of either partner were specifically co-purified with IGF2BP2-HA, indicating that ZIKV infection does not significantly change their association." (PMID 39565347, 2024). "Overall, these data show that ZIKV infection induces the physical recruitment of IGF2BP2 to the replication compartment, and further suggest that IGF2BP2 might contribute to vRNA synthesis through interactions with NS5 polymerase." (PMID 39565347, 2024). "Since IGF2BP2 associates with NS5 and vRNA and accumulates in the viral replication compartment, we hypothesized that ZIKV infection induces a remodeling of IGF2BP2 RNP, notably regarding its content in endogenous mRNA partners." (PMID 39565347, 2024). "Zika virus (ZIKV) infection does not significantly impact the association of IGF2BP2 with IGF2BP1, IGF2BP3, and YBX1." (PMID 39565347, 2024). "Finally, the analysis of immunopurified IGF2BP2 complex using quantitative mass spectrometry and RT-qPCR revealed that ZIKV infection alters the protein and RNA interactomes of IGF2BP2." (PMID 39565347, 2024). "Next, to assess our hypothesis of a ZIKV-remodeled IGF2BP2 RNP, we investigated whether ZIKV infection changes the protein interaction profile of IGF2BP2." (PMID 39565347, 2024). "Finally, ZIKV infection alters the protein and RNA interactomes of IGF2BP2." (PMID 39565347, 2024).
tumor (257 papers, 2011 to 2026). "As tumorsphere models better simulate tumor biology compared with cells cultivated in monolayers, we also investigated the effects of IGF2BP2 loss under these conditions." (PMID 40347943, 2025). "In our investigation, we identified insulin-like growth factor 2 mRNA binding protein 2 (IGF2BP2) as the most markedly upregulated RBP in tumor cells and cancer-associated fibroblasts (CAFs)." (PMID 40362183, 2025). "Clinical observations from The Cancer Genome Atlas database showed that elevated IGF2BP2 levels in PCa tissues were significantly associated with higher Gleason scores and exhibited a trend toward correlating with tumor metastasis." (PMID 40084251, 2025). "In summary, our findings establish IGF2BP2 as the most prominently upregulated RBP in tumor cells and CAFs, highlighting its potential as a diagnostic and prognostic biomarker for OSCC." (PMID 40362183, 2025). "In these malignancies, IGF2BP2 levels have been associated with tumor progression, poorer prognosis, and lower overall survival." (PMID 40243425, 2025). "IGF2BP2 is highly expressed in COAD tumor tissues and, among m6A reader proteins implicated in mRNA stability, only IGF2BP2 exhibits a significant positive correlation with MTA1 expression in COAD." (PMID 39300486, 2024). "In many cancer types, upregulation of IGF2BP2 has been associated with poor disease prognosis 16-18, implicating IGF2BP2 as a tumor promoter." (PMID 38250159, 2024). "IGF2BP2 has been implicated in suppressing anti-tumor immune responses, enhancing the function of immunosuppressive cells, adapting to hypoxic conditions, and driving cancer metabolism, angiogenesis, drug resistance, metastasis, and cell cycle progression." (PMID 39596216, 2024). "Previous studies have found that IGF2BP2 overexpression occurs in a variety of cancers and is associated with tumor growth and migration." (PMID 39550498, 2024). "It has been reported that forms of IGF2BP2 exosomes migrate to endothelial cells, promote angiogenesis in LUAD, cause tumor invasion and poor prognosis, and IGF2BP2 knockdown inhibits tumor metastasis and angiogenesis." (PMID 39033180, 2024). "IGF2BP2 expression in primary tumor tissue was significantly associated with resistance to selumetinib, gefitinib, and regorafenib in PDOs and to 5-fluorouracil and oxaliplatin in PDX in vivo." (PMID 37248468, 2023). "For IGF2BP2, its splice variant p62 has been shown to influence chemoresistance due to antiapoptotic actions and a more aggressive tumor phenotype in hepatocellular carcinoma (HCC)." (PMID 37248468, 2023). "A body of data disclose the causal role of IGF2BP2 in cancer etiology, and find that IGF2BP2 is overexpressed during carcinogenesis and early development, which causes the tumorigenic phenotype, tumor progression and unfavorable prognosis." (PMID 37915103, 2023). "Our study also revealed that IGF2BP2 is closely associated with remodeling immune microenvironment and that high IGF2BP2 expression is accompanied by a decrease in the number of tumor-infiltrating CD8+ T cells." (PMID 35299748, 2022). "Experiments with IGF2BP2-deficient mice has indicated that IGF2BP2 is a tumor-promoting factor that facilitates the progression of cancer as well as metastasis." (PMID 34980207, 2022). "N6-methyladenosine (m6A) RNA modification is an emerging epigenetic regulatory mechanism for gene expression, and as a novel m6A reader protein, IGF2BP2 has been implicated in tumor progression and metastasis." (PMID 34980207, 2022). "Two mutated, amplified, and over-expressed tumor antigens, IGF2BP2 and MMP9, were found to be associated with clinical outcomes and the abundance of antigen-presenting cells (APCs)." (PMID 36569935, 2022). "Among these m6A regulatory genes, IGF2BP2 was upregulated in HNSCC tumor tissues, and high IGF2BP2 expression was associated with poor patient OS in seven cancer types, including HNSCC." (PMID 33816266, 2021).
tumor (continued). "Previous studies revealed that IGF2BP2 was upregulated in multiple tumors and was associated with tumor growth, migration, and energy metabolism." (PMID 34239534, 2021). "In conclusion, our study demonstrated that IGF2BP2 is highly expressed in HNSCC tumor tissues and is associated with tumor progression and poor survival." (PMID 32391379, 2020). "Furthermore, IGF2BP2 deficiency impaired tumor-associated macrophage (TAM)-like polarization in vitro, as evidenced by decreased expression of TAM markers, such as Mrc1, Mmp2, and Il10." (PMID 41943844, 2026). "These consistent findings suggest that the expression of PBX2, PRMT1, SMARCC1, and IGF2BP2 in tumor tissues could serve as reliable diagnostic markers for HNSCC due to their high sensitivity and specificity." (PMID 40270464, 2025). "Next, to clarify impacts of IGF2BP2 genetic polymorphisms on PCa clinicopathological characteristics, we analyzed factors such as pathologic staging, clinical staging, Gleason grade groups, tumor invasion, D'Amico classification, and BCR." (PMID 40084251, 2025). "To expand upon these in silico findings, we examined whether IGF2BP2 loss reduces tumor growth in TNBC xenograft models in vivo." (PMID 40347943, 2025). "The overexpression of IGF2BP2 might be driven by multiple mechanisms, including the loss of tumour-suppressive miRNAs, gene amplification and upregulation mediated by the lncRNA LINC00901." (PMID 40427100, 2025). "Interestingly, high IGF2BP2 expression is often found in high-risk tumours that exhibit lower immune response activity." (PMID 40427100, 2025). "In addition, USP14 can enhance CXCL2 expression by stabilizing the m6A reader IGF2BP2 in tumor-associated macrophages." (PMID 40986143, 2025). "Furthermore, compared to A549/DDP + DDP group, IGF2BP2 deficiency further reduced the levels of CD133 and IGF2BP2 in tumor tissues from A549/DDP xenograft mice." (PMID 39731162, 2024). "Moreover, in CC, upregulated IGF2BP2 expression in CC tissues is positively associated with the tumor stage." (PMID 38721006, 2024). "Additionally, IGF2BP2 deficiency led to an additional reduction in both tumor volume and weight compared to the A549/DDP + DDP group." (PMID 39731162, 2024). "In addition, augmented IGF2BP2 expression was associated with decreased survival, advanced clinical stage, and larger tumor size in HNSC patients." (PMID 38250159, 2024). "Moreover, correlation analysis in TCGA‐BLCA demonstrated a strong association between IGF2BP2 expression and immunosuppressive cells, including M2 macrophages, Tregs, suggesting its role in shaping an immunosuppressive tumor microenvironment (TME)." (PMID 39711402, 2024). "Interestingly, a higher IGF2BP2 immunohistochemical staining intensity was associated with more advanced tumor stages in tissue microarrays (n = 80)." (PMID 37248468, 2023). "Finally, the association among IGF2BP2, its co-expressed genes, and tumor-infiltrating immune cells (TICs) was investigated." (PMID 35129592, 2022). "Here, we validated that circ‐TNPO3 could bind directly to IGF2BP2, belonging to the IGF2BPs family, which is associated with tumour development." (PMID 35876041, 2022). "Gene Set Enrichment Analysis (GSEA) indicated that IGF2BP2 was correlated with multiple biological processes associated with cancer, of which the most significant processes were relevant to cancer cell cycle, cell immortalization and tumor immunity." (PMID 33082301, 2020). "Furthermore, statistical analysis of the 20 HCC patients’ tumor tissues showed that expression of IGF2BP2 was associated with tumor size (p = 0.031)." (PMID 33224879, 2020).